ENSG00000256100 (novel transcript)
Gene: Long non-coding RNA gene on chromosome 11 (63,974,620 to 63,988,346, forward strand). Ensembl gene ENSG00000256100.
Genetic constraint (gnomAD): Loss-of-function variants: 6 observed, 6.36 expected, observed/expected ratio (o/e) 0.94, 90% interval 0.51 to 1.73. That is too few expected variants to judge how well the gene tolerates losing a copy. Missense variants: 102 observed, 86.77 expected, observed/expected ratio (o/e) 1.18, 90% interval 1 to 1.39. Synonymous variants: 59 observed, 49.42 expected, observed/expected ratio (o/e) 1.19, 90% interval 0.97 to 1.48.